ELOVL2-AS1 (ELOVL2 antisense RNA 1)
Gene: Long non-coding RNA gene on chromosome 6 (11,043,482 to 11,079,154, forward strand). Ensembl gene ENSG00000230314.
Gene Ontology:
Biological process: RNA processing
Cellular component: nucleolus